BSX (brain specific homeobox)
Description:
DNA binding protein that function as transcriptional activator. Is essential for normal postnatal growth and nursing. Is an essential factor for neuronal neuropeptide Y and agouti-related peptide function and locomotory behavior in the control of energy balance (By similarity).
Synonyms: BSX1
Tractability: No criterion of Open Targets' tractability assessment is met for any kind of drug.
Gene: Protein-coding gene on chromosome 11 (122,977,570 to 122,981,834, reverse strand). Ensembl gene ENSG00000188909.
Subcellular location: Nucleus
Gene Ontology:
Molecular function: sequence-specific double-stranded DNA binding; DNA-binding transcription factor activity, RNA polymerase II-specific; RNA polymerase II cis-regulatory region sequence-specific DNA binding; DNA binding; sequence-specific DNA binding
Biological process: cell differentiation; eating behavior; regulation of transcription by RNA polymerase II; stem cell population maintenance; regulation of DNA-templated transcription
Cellular component: chromatin; nucleus; transcription regulator complex
Genetic constraint (gnomAD): Loss-of-function variants: 12 observed, 16.59 expected, observed/expected ratio (o/e) 0.72, 90% interval 0.46 to 1.17. The upper end of that interval is the gene's LOEUF score, 1.17, which puts it in group 5 of 6, group 1 being the genes least tolerant of losing a copy. Missense variants: 292 observed, 306.61 expected, observed/expected ratio (o/e) 0.95, 90% interval 0.87 to 1.05. Synonymous variants: 160 observed, 137.91 expected, observed/expected ratio (o/e) 1.16, 90% interval 1.02 to 1.32.
Homologues: Orthologues: chimpanzee BSX (99% identical), macaque BSX (99% identical), rabbit BSX (97% identical), pig BSX (97% identical), dog BSX (97% identical), mouse Bsx (96% identical), rat Bsx (94% identical), guinea pig BSX (94% identical), tropical clawed frog bsx (72% identical), Caenorhabditis elegans ceh-43 (21% identical), Drosophila melanogaster Dll (19% identical). Paralogues in human: DLX3 (23% identical), DLX5 (23% identical), DLX2 (21% identical), DLX1 (21% identical), DLX4 (21% identical), DLX6 (21% identical), VENTX (20% identical), NANOG (18% identical), NANOGP8 (18% identical).
Diseases named in the same sentence as BSX in open-access papers:
BSX is named in the same sentence as 2 diseases in open-access papers, as found by Europe PMC text mining. Sharing a sentence is not in itself a finding about the gene and the disease. The quoted sentences say what the papers report.
Jacobsen syndrome (1 paper, 2020). A multiple congenital anomaly/intellectual disability contiguous gene syndrome caused by partial deletion of the long arm of chromosome 11. "Moreover, our data might help to reevaluate endocrine features of patients suffering from Jacobsen syndrome, a disease in which chromosome 11 deletions which encompass the BSX locus, were implicated." (PMID 32581684, 2020).
cancer (1 paper, 2021). A tumor composed of atypical neoplastic, often pleomorphic cells that invade other tissues. "In terms of cancer-driven mutations, the HRSI group has two significant mutations, including HRAS and KLF5, while the LRSI group has three significant mutations, including ATP6V0A2, BSX, and VNN1." (PMID 34504628, 2021).